TNF (tumor necrosis factor)
Diseases named in the same sentence as TNF in open-access papers (continued):
Sharing a sentence is not in itself a finding about the gene and the disease.
HIV-1 infection (continued). "Serum concentrations of TNFα have been shown to increase as HIV-1 infection progresses, suggesting that TNFα may contribute to disease progression." (PMID 21599974, 2011). "Experiments using tissue explants have shown that gram-positive bacteria such as Staphylococcus aureus, Group B Streptococcus and genital pathogens such as Candida albicans and Neisseria gonorrhea increase Langerhans' cells susceptibility to HIV-1 infection via TLR2 agonists and TNF-α production." (PMID 20066050, 2010). "As expected, HIV-1 infection induced expression of IL-1β, IL-6, TNF-α and CXCL8." (PMID 20877724, 2010). "Macrophages release various inflammatory cytokines such as IL-1β and TNF-α upon HIV-1 infection." (PMID 19404407, 2009). "Although TNF-α may be important in regulating immune response and inducing survival and regeneration in HSCs, impaired regulation in HIV-1 infection and TNF-α-induced reactivation of HIV-1 may reduce regenerative capacity, alter quiescence status, and diminish HSC population." (PMID 38675885, 2024). "As revealed from recent findings, HIV-1 infection is capable of creating inflammation surroundings induced by virus proteins [transactivator of transcription (Tat) and gp (glycoprotein) 120] and pro-inflammation cell factors [tumor necrosis factor-alpha (TNF-α), interleukin (IL)-8, IL-6, and IL-1β]." (PMID 36927791, 2023). "Finally, to directly establish the role of IL-1β in modulating CCR5 expression via miR-103 in the context of HIV-1 infection, we pretreated MDMs with the Supnt alone or in the presence of either neutralizing anti-IL-1β, anti-TNF-α, or a combination of both antibodies (Abs)." (PMID 32994328, 2020). "Interestingly, human immunodeficiency virus 1 (HIV-1) infection induces TNFα expression." (PMID 27351838, 2016). "HIV-1 has been linked to the up-regulation of cytokines and in fact HIV-1 Tat upregulates IL-12 and TNF-α and -β expression in monocyte-derived dendritic cells, suggesting an advantage of nanoATV in the regulation of pro-inflammatory cytokines during HIV-1 infection." (PMID 25608975, 2015). "One potential explanation may be that the subpopulation of CD4+ T cells expressing TNF-α and CTLA-4 or PD-1 may be less readily able to support productive HIV-1 infection despite evidence that CTLA-4 signaling may be associated with increased CCR5 expression and enhanced susceptibility to infection." (PMID 22479542, 2012). "Human immunodeficiency virus type 1 (HIV-1) infection frequently causes neurologic disease, which is the result of viral replication and activation of macrophages and microglia in the CNS, and subsequent secretion of high levels of neurotoxic products, including tumor necrosis factor-α (TNF-α)." (PMID 21569583, 2011). "Cytokines such as TNF-α and IFN-γ secreted by NK cells, including TIGIT−NK cells and TIGIT+NK cells, decreased in the first, twelfth month of HIV-1 infection compared with HIV-1-negative donors." (PMID 33717085, 2021). "Despite the immunodeficiency during HIV-1 infection, HIV-1 exploits our cellular defence arsenal by escaping cell-mediated lysis, yet HIV-1 infectivity is enhanced via C5a release of TNF-α and IL-6." (PMID 34502066, 2021). "It is worth mentioning that some other components of exosomes also inhibit HIV-1 infection, mainly different cytokines, which include interleukins (ILs), interferon-alpha (IFN-α), interferon-beta (IFN-β), and tumor necrosis factor (TNF-α)." (PMID 32471020, 2020). "HIV-1 infection increases expression of inflammatory markers (TLR4, TNF-α, and NF-κB) and upregulates Sur1 and Trpm4 in astrocytes of Tg26 mouse brain tissues." (PMID 33293383, 2020). "Cytokines affected by HHODC in this study, IL-2, IL-6, TNF-α, and IFN-γ, are documented as being among the many biomarkers affected by HIV-1 infection due to immune dysfunction." (PMID 29027985, 2017).
HIV-1 infection (continued). "Chronic inflammation in HIV-1 infection is characterized by the detection of soluble markers of immune activation, including, among others, neopterin, β2 microglobulin, soluble CD30, TNF, and the soluble TNFR2 (sTNFR2)." (PMID 28358311, 2017). "In HIV-1 infection, IFN-γ single positive mycobacteria-specific CD4+ T cells were decreased, while the frequency of polyfunctional cells (IFN-γ+IL-2+TNF-α+) remained unchanged." (PMID 27865393, 2016). "The elevation of multifunctional cytokines such as IFNγ and TNFα, can either enhance or control HIV-1 infection depending on the clinical stage of HIV-1 infection." (PMID 24454311, 2014). "A number of pro-inflammatory cytokines (TNF-α, IL-1β, IL-6, IFN-γ) and oxidative stress markers (such as nitric oxide) are known to be elevated during brain HIV-1 infection." (PMID 24884548, 2014). "In this regard, it has been reported that HIV-1 infection augments L. infantum multiplication in MDMs, and that, conversely, Leishmania enhances HIV-1 replication through inducing the production of TNF-α and IL-1α." (PMID 22412921, 2012). "Altogether, our data provide evidence that both Gag and TNFα make use of Syx6-mediated trafficking machinery and suggest that Gag expression does not inhibit but rather facilitates TNFα secretion in HIV-1 infection." (PMID 38280430, 2024). "HIV-1 infection has been reported to inhibit macrophage apoptosis in response to Mtb infection, potentially through HIV-1 Nef inhibition of tumor necrosis factor alpha (TNF-α) production." (PMID 38412342, 2024). "Concordantly, we observed a rapid elevation in the plasma levels of several pro-inflammatory cytokines such as IFN-γ, IL-18, and IP-10 but not of IL-6 and TNFα that remained below the LOD in most of mice plasma upon HIV-1 infection." (PMID 36800238, 2023). "Gp120 can contribute to enhanced HIV-1 infection of the CNS and the corresponding neuroinflammation through disruption of the BBB, increased cytokine secretion, specifically TNFα via activation of microglia and astrocytes, and increased neuronal sensitivity to calcium fluctuation." (PMID 35203372, 2022). "Taken together, these data indicate that chronic HIV-1 infection drives the expansion of CD56neg NK cells that express lower levels of granzyme B and perforin and display defective production of cytokines, such as IFN-γ and TNF-α." (PMID 35069597, 2021). "Following HIV-1 infection of THP-1 macrophages, we first hypothesized that TNF-α would be induced upon infection." (PMID 33762317, 2021). "Furthermore, in including the first and third months of acute HIV-1 infection, more NK cells expressed TIGIT, fewer NK cells released TNF-α, and there was a lower MFI of TNF-α expressed by NK cells, especially in the third month of infection." (PMID 33717085, 2021). "The expression level of IL-1β and IL-6 remained below the threshold of detection in MF supernatants even after HIV-1 infection, and the level of TNF-α mRNA was not modified upon infection." (PMID 32365752, 2020). "Our data demonstrate that HIV-1 infection not only depletes ILC1s but also leads to their activation and functional impairment, as indicated by the significant decrease observed in their production of cytokines, including IFN-γ and TNF-α." (PMID 29304123, 2018). "Many studies have previously reported a correlation between the observed increase in the production of pro-inflammatory cytokines IL-1β, IL-6, IL-18 and TNF-α; and IFN inducible chemokines CXCL9, CXCL10 and CXCL11 during the course of HIV-1 infection and the up regulation of HIV-1 replication." (PMID 29373606, 2018). "In addition, we will address the impact of the TNF/TNFR pathway on the immune activation and the formation of viral reservoirs during the course of HIV-1 infection." (PMID 28358311, 2017).
HIV-1 infection (continued). "In order to confirm this hypothesis we utilized the ectopic expression of HIV-1 ENV-YFP chimeric protein in RAW 264.7 cells, which mimics the HIV-1 infection of macrophages, and tested their responsiveness to LTA by measuring TNFα secretion." (PMID 25121610, 2014). "There is a lack of comparative data on the influence of TNF-α SNPs on various clinical cohorts of HIV-1 infections like fast progressors, elite controllers, long-term non-progressors and exposed but seronegative individuals." (PMID 24837009, 2014). "We found that ex vivo CD4+ T cells and CD8+ T cells, as well as HIV-specific CD8+ T cells from individuals with chronic HIV-1 infection are primed to undergo apoptosis through CD95/Fas but not TRAIL or TNFα signaling." (PMID 24130482, 2013). "Interestingly, the percentage of TNF-α -producing monocytes following TLR8 stimulation strongly positively correlated with HIV-1 RNA levels both in acute and chronic HIV-1 infection." (PMID 23818854, 2013). "Irrespective of the lack of productive HIV-1 infection, co-treatment of astrocytes with TNF-α and HIV-1 particles for 48 h showed upregulation of CXCL10 expression." (PMID 23078780, 2012). "IL-1β along with TNF-α is also known to reactivate latent or non-production HIV-1 infection of astrocytes in an NF-κB dependent manner." (PMID 22027397, 2011). "IL-1β along with TNF-α is known to reactivate latent or non-productive HIV-1 infection of astrocytes in an NF-κB dependent manner." (PMID 22027397, 2011). "We may speculate that the co-occurrence of maternal HIV-1 infection, use of HAART and hard drugs, all contributed to a higher stimulation of maternal immune cells leading to a larger baseline production of TNF-α in short term culture." (PMID 21291536, 2011). "Bryostatin reactivated latent HIV-1 infection in monocytic cells more robustly than PMA and TNF-α." (PMID 20585398, 2010). "Not surprisingly, HIV-1 infection alters the PKC phosphorylation pathway to stimulate TNF-α production by monocytes as well as other cytokines and growth factors such as IL-6, IL-10, and MCP-1." (PMID 20604950, 2010). "We found Tat-induced methylation variations in genes such as TNF, CD1C, and CD1D, belonging to pathways involved in the binding, processing, and presentation of lipid antigens, immune response, and inflammatory pathways, which are processes well-documented during HIV-1 infection." (PMID 40103825, 2025). "Interestingly, HIV-1 infection facilitated TNFα secretion, and this enhancement did not occur in Syx6-depleted cells." (PMID 38280430, 2024). "In human cells, increased expression of proinflammatory cytokines such as tumor necrosis factor alpha (TNF-α), interleukin 6 (IL-6), and interleukin-12, which contribute to HIV-induced immune activation, can be triggered by Toll-like receptor (TLR) 8 sensing of HIV-1 infection." (PMID 39459950, 2024). "As expected, HIV-1 infection in the vehicle group induced a potent cytokine storm with elevated plasma levels of the inflammasome-related cytokines IL-18 but also IFN-γ, IP-10 and TNFα when compared to day 10 before infection (p<0.05; 0.01; 0.05; 0.001; 0.01; 0.001, respectively)." (PMID 36800238, 2023). "Additionally, the trifunctionality of TIGIT+NK and TIGIT−NK cells in secreting CD107a, TNF-α and IFN-γ might be decreased in both acute and chronic HIV-1 infection." (PMID 33717085, 2021). "To assess if the D1D2CAR transduced T cells respond to HIV-1 infection, we co-incubated D1D2CAR transduced CD8+ T cells with HIV-infected or uninfected T1 cells and measured production of intracellular cytokines interferon-γ (IFN-γ) and tumor necrosis factor alpha (TNF-α)." (PMID 33793675, 2021). "In contrast, the apparent dichotomous observation of greatly increased barrier dysfunction and leakage along with decreased TNF-α and IL-1α production after treatment with MPA and HIV-1 challenge indicate that MPA may still lead to enhanced HIV-1 infection due to increased viral entry." (PMID 31546582, 2019).
HIV-1 infection (continued). "Alternatively, polyclonal bystander activation of non-specific and low affinity B cells by cytokines and growth factors (e.g. IFN-a, TNF-a, IL-4, IL-10, BAFF) and surface CD40L, which may be over-expressed in untreated HIV-1 infection, may also affect the selection process." (PMID 24409278, 2014). "In this way, TNF-α secretion might not be the main way for NK cells to control HIV-1 infection, instead other mechanisms may account for the viral control such as the modification of the NK cell receptor repertoire." (PMID 24156302, 2013). "Moreover, E. natalensis phytochemicals were significantly enriched in the HIV-1 infection pathway (hsa05170), with overlapping genes converging on PI3K–Akt–MTOR signaling, NFκβ activation, MAPK cascades, calcium signaling, Toll-like receptor signaling, TNF signaling, and apoptotic pathways." (PMID 41011481, 2025).
Myocardial fibrosis (123 papers, 2012 to 2026). "The molecules TGF-β1, TNF-α, IL-6, galectin-3, and galectin-1 are critically involved in the cardiac inflammatory and profibrotic cascade, and they have been linked to myocardial fibrosis severity and to structural and electrical atrial remodeling." (PMID 41590667, 2026). "Elevated levels of TNF-α have been linked to cardiomyocyte apoptosis, mitochondrial dysfunction, and myocardial fibrosis, which lead to deterioration of heart function." (PMID 40943854, 2025). "Elevated TNF-α levels have been linked to cardiomyocyte apoptosis, mitochondrial dysfunction, and myocardial fibrosis, all of which contribute to progressive systolic dysfunction and adverse clinical outcomes." (PMID 40943854, 2025). "It releases proinflammatory cytokines such as tumor necrosis factor-alpha, interleukin-1-beta, and interleukin-6, which can cause variable irreversible changes in the myocardium structure, including myocardial fibrosis." (PMID 31347351, 2019). "It decreased myocardial fibrosis and transmurality of the infarct, associated with increased eNOS, p-eNOS, and IL-10 along with decreased expression of TNF-α, IL-6 and iNOS." (PMID 25807532, 2015). "Interleukin-6, interleukin-1 beta and the tumour necrosis factor (TNF)-alpha may cause myocyte damage via the major histocompatibility complex-1, by local nitric oxide release and myocardial fibrosis." (PMID 36088383, 2022). "TNF-α has been directly implicated in the development of myocardial fibrosis." (PMID 23152884, 2012). "Carfilzomib exacerbates these effects by activating the NF-κB pathway in cardiac tissue, promoting inflammatory cytokine release (e.g., TNF-α, IL-6) and myocardial fibrosis." (PMID 40969263, 2025). "Semaglutide, a GLP-1 analog, has been shown to reduce TNF-α and other proinflammatory biomarkers and inhibit myocardial fibrosis signaling pathways." (PMID 40429692, 2025). "Cytokines such as interleukin-1, interleukin-6, tumor necrosis factor-alpha, and interleukin-17 are involved in promoting myocardial fibrosis, ion channel dysfunction, and autonomic dysregulation, which contribute to arrhythmic events." (PMID 40901119, 2025). "Inflammatory factors include tumor necrosis factor (TNF), galectin-3 (gal-3), nuclear factor kappa-B (NF-κB) and interleukin (IL), which act on effector cells and promote myocardial fibrosis through multiple pathways." (PMID 40881586, 2025). "In the study of dilated cardiomyopathy, B cells secreted TNF-α to exert proinflammatory effects and participate in and promote the process of myocardial fibrosis." (PMID 40881586, 2025). "IL-6 and TNF-α can accelerate the secretion of a large amount of collagen and myocardial fibrosis in myocardial tissue, and finally damage myocardial function." (PMID 40547034, 2025). "Persistent NF-κB activation promotes chronic low-grade inflammation, characterized by overexpression of TNF-α, IL-1β, and IL-6, which contributes to cardiomyocyte apoptosis and myocardial fibrosis." (PMID 41158877, 2025). "These early changes were associated with higher circulating TNF-α, decreased myocardial AMPK activation, and more severe myocardial fibrosis." (PMID 41155489, 2025). "Myocardial fibroblasts secrete TNF-α in response to different types of injury; however, excessive TNF-α secretion leads to myocardial fibrosis." (PMID 40881586, 2025). "Chronic inflammation driven by TNF-α promotes myocardial fibrosis, ventricular dilation, and progressive dysfunction in preclinical models, but this effect is more difficult to isolate in human trials due to compensatory mechanisms and comorbidities." (PMID 41011058, 2025). "And sterile inflammation is closely associated with the levels of pro-inflammatory factors (e.g., TNF-α, IL-6, and IL-1β) that can induce myocardial fibrosis." (PMID 40881586, 2025). "These processes, combined with upregulated pro-inflammatory cytokines (e.g., TNF-α, IL-6), foster myocardial fibrosis and electrical remodeling." (PMID 41011065, 2025).